HERC2 (HECT and RLD domain containing E3 ubiquitin protein ligase 2)
Diseases named in the same sentence as HERC2 in open-access papers (continued):
Sharing a sentence is not in itself a finding about the gene and the disease.
cancer (26 papers, 2016 to 2025). A tumor composed of atypical neoplastic, often pleomorphic cells that invade other tissues. "Homologous to the C‐terminus of E6AP (HECT) and RCC1‐like domain (RLD)‐containing protein 2 (HERC2) is a large, 528 kDa E3 ubiquitin ligase that is associated with cancer, oculocutaneous albanism type 2, Prader‐Willi syndrome, and other neurological diseases." (PMID 39565083, 2024). "For example, HERC2 mutations are associated with breast, skin (melanoma), gastric, colorectal, and haematological (leukaemia) cancers." (PMID 36241744, 2022). "The E3 ubiquitin ligase HERC2 has been linked to neurological diseases and cancer, however it remains a poorly characterized human protein." (PMID 35411094, 2022). "We propose that NCOA4 is instead dysregulated at the protein level as a result of altered HERC2 E3 ubiquitin ligase activity; indeed, HERC2 is mutated up to 20% in various cancers (obtained from cBioportal)." (PMID 29435183, 2018). "The number of mutated tumours underlying each model varied from 8 (biallelic SMARCA-d in cancers of unknown primary) to 22 (monoallelic HERC2-d in skin)." (PMID 36883553, 2023). "Loss of this HERC2-dependent replication control could lead to genomic instability in HERC2-deficient cancers that may in turn provide opportunities for therapeutic strategies." (PMID 31582797, 2019). "First, we conducted a haplotype analysis adjusted for sex and family history of cancer for the variants of the OCA2 and HERC2 genes and a separate analysis for the variants of the MC1R gene." (PMID 40429816, 2025). "HERC2 isfrequently downregulated in numerous types of cancers due to its critical role onchromosomal stability, and variants in this gene have been associated with developmentaldelay." (PMID 38259032, 2024). "We assumed that the regulatory effect of HERC2 on STAT3 signaling participates in the crosstalk between cancer stemness and immune evasion." (PMID 36721234, 2023). "In conclusion, our study identified HERC2 as a novel regulator for cancer stemness and immune evasion in inflammation-related HCC." (PMID 36721234, 2023). "Studies have shown that HECT domain and RCC1-like domain 2 (HERC2) enhance cancer stemness and PD-L1-mediated immune escape of HCC cells, which is associated with activation of the STAT3 pathway during the inflammation-cancer transformation." (PMID 38155974, 2023). "It is conceivable that HERC2 targeted drug development needs to be focused on enhancing the onco-suppressive activities of HERC2 to control the progression of cancer." (PMID 33869064, 2021). "HERC2 is an E3 ligase involved in tumor progression through degradation of cancer-specific substrates." (PMID 33644029, 2020). "HERC2 enhanced the stemness and PD-L1-mediated immune evasion of HCC cells, which is associated with the activation of signal transducer and activator of transcription 3 (STAT3) pathway during the inflammation-cancer transition." (PMID 36721234, 2023). "Since HERC2 is downregulated in numerous cancers, this effect may be clinically relevant considering the beneficial effects of CX-5461 in cancer treatments." (PMID 33432007, 2021). "Inactivation of HERC2 E3 activity in cells inhibited the ubiquitination of RPA2 and caused RPA accumulation in the complexes, resulting in G4 accumulation and hypersensitivity to G4 stabilizers in cancer cells." (PMID 31582797, 2019).
cancer (continued). "Expanded studies on HERC2 could prove to be pivotal in the development of new immunotherapeutic treatments that target specific HECT E3 protein-protein interactions in the cell to elicit a specific intracellular immunological response against cancers." (PMID 33869064, 2021). "Genes at two of these loci, HERC2/OCA2 and IRF4, are involved in pigmentation, while the third, CLPTM1L/TERT, is a known cancer driver." (PMID 40495383, 2025). "Furthermore, we present unexpected predictive models of several DDR deficiencies; ATRX and IDH1 deficiency in cancers of the central nervous systems (CNSs), HERC2 and CDKN2A deficiency in skin, PTEN deficiency in cancers of the CNS and uterus, and SMARCA4 deficiency in cancers of unknown primary." (PMID 36883553, 2023). "Inhibition of ASPM expression promotes HERC2-mediated BRCA1 degradation, compromises HR repair efficiency and chromosome stability, and sensitizes cancer cells to ionizing radiation." (PMID 34142045, 2021). "On the other hand, “hub genes” of four other modules contain POU2F3 (↑), CENPH (↑), PCSK6 (↑) and HERC2 (↑), BCAR3 (↑), DOHH (↑), NLK (↑), SCN2A (↑), CACNA2D3 (↓) and CTNND2 (↓), which were commonly reported related to cancer." (PMID 27602771, 2016).
tumor (22 papers, 2014 to 2026). "This patient’s tumor also harbored a HERC2 heterozygous mutation in the functional domain (p.G3027R)." (PMID 38755180, 2024). "However, one irradiated tumor harbored a missense mutation in HERC2, a gene essential to DNA repair." (PMID 34816314, 2022). "Several HERC2 mutations have been associated with a wide number of tumours." (PMID 36241744, 2022). "HERC2 has been found to contribute to double‐stranded DNA break repairs, tumor suppression, maintaining centrosome architecture, and ubiquitylation." (PMID 39565083, 2024). "PALB2 showed outlier high expression (99th percentile) as did other genes involved in HR including BRCA1 (94th percentile), BRCA2 (100th percentile), and HERC2 (100th percentile) in this tumor." (PMID 38755180, 2024). "The result demonstrated the inhibitory effect of HERC2 on anti-tumor immunity, as indicated by impaired activation of CD8+ T cells, CD4+ T cells, and NK cells in the coculture system of PBMCs with HERC2-overexpressed HCC cells." (PMID 36721234, 2023). "Increased tumor size was observed in mice injected with diluted HERC2-overexpressing HCC cells compared to their counterparts." (PMID 36721234, 2023). "In contrast, HERC2 overexpression promoted tumor development and progression in the orthotopic transplantation HCC model." (PMID 36721234, 2023). "One tumor, VN-MPNST2, harbored a mutation in HERC2, a gene coding for an E3 ubiquitin protein ligase." (PMID 34816314, 2022). "For example, relevant studies have found that the variants rs12913832 in HERC2, rs3798577 in ESR1, and rs183471242 on chromosome 11 are linked to both MM risk and tumour thickness, suggesting that germline genetic variation plays a crucial role in disease development and progression." (PMID 40305358, 2025). "Recent proteomic studies have shown that HERC2 interacts with many proteins involved in the DNA damage response, tumor suppression, centrosome architecture, intracellular protein transport/trafficking, translation, iron metabolism, and proteasomal degradation via ubiquitylation." (PMID 39565083, 2024). "Notably, the high expression of HERC2 in tumor tissues was related to inflammatory immune subtype, which indicated a potential role of HERC2 in inflammation-related liver tumorigenesis." (PMID 36721234, 2023). "Similarly, tumor tissues exhibited higher HERC2 levels than the matched adjacent tissues in HCC patients." (PMID 36721234, 2023). "Notably, HERC2-positive tumor cells expressed higher IL-6/JAK/STAT3-related genes and STAT3-targeted genes than HERC2-negative tumor cells, which also indicated the regulatory role of HERC2 in JAK2/STAT3 signaling." (PMID 36721234, 2023). "We found elevated HERC2 expression in tumor tissues compared to the normal tissues." (PMID 36721234, 2023). "We thus investigated whether HERC2 regulates anti-tumor T cell immunity via modulating PD-L1 expression in HCC cells." (PMID 36721234, 2023). "No genes were uniquely mutated in any of the tumours of patients with a relapse, while only one gene, HERC2, was uniquely mutated in the primaries of 4/18 nonrecurrent patients and in none of the primaries or recurrences of patients with relapses (p = 0.1)." (PMID 35008243, 2021).
tumor (continued). "Key predictors included clinical variables (age, tumor size, NPI, radiotherapy) and molecular markers (ATM, HERC2, AKT2, FOXO3, CYP3A43)." (PMID 41300329, 2025). "Feature selection was performed using the Boruta algorithm, which revealed that both clinical parameters (e.g., age, tumor size, NPI, radiotherapy) and transcriptomic biomarkers (e.g., ATM, HERC2, AKT2, CYP3A43, FOXO3) provided strong prognostic contributions." (PMID 41300329, 2025). "Taken together, our findings demonstrated a novel function of HERC2/USP20 in coordinating CHK1 activation by modulating CLASPIN stability, which ultimately promotes genome stability and suppresses tumor growth." (PMID 25326330, 2014). "The tumor cells were divided into HERC2-positive and HERC2-negative groups based on the HERC2 expression." (PMID 36721234, 2023). "Our study identified that HERC2 serves as an opposing force actively participating in the homeostatic control of PD-L1 in HCC, and interfering with the expression or function of HERC2 might help promote the anti-tumor efficiency of immune checkpoint-based therapy." (PMID 36721234, 2023). "To evaluate the predictive power of HERC2 and IRF4 genotypes, we built a genetic classifier of chromosome 3 status and applied this classifier to predict outcomes in patients for whom tumor status was not available." (PMID 41377059, 2026). "However, the gene‐level integrated analysis revealed heterogeneity in expression, copy number variation and methylation status of MDM4, RRAGC, HERC2, BIRC3 and TSC2 genes within and across individual tumours, suggesting that they may not be ideal biomarkers for PDAC." (PMID 35061935, 2022).
neurodevelopmental disorder (9 papers, 2016 to 2026). A behavioral and cognitive disorder with onset during the developmental period that involves impaired or aberrant development of intellectual, motor, or social functions. "The E3994A mutation in the RLD3 domain of HERC2 was found in a single patient, so its causal role in the patient’s neurodevelopmental disorders should be considered provisional." (PMID 37480851, 2023). "On the other hand, germ-line mutations in HERC2 are also associated with an autosomal recessive neurodevelopmental disorder (OMIM #615516)." (PMID 36902336, 2023). "This study extends the genotype–phenotype correlation for HERC2 variants to include a distinct lethal neurodevelopmental disorder, highlighting the importance of further characterisation for HERC2-related disorders." (PMID 32571899, 2021). "Whether the alterations in these MAPK signaling pathways are associated with clinical outcomes in the neurodevelopmental disorders caused by mutations in HERC1 or HERC2 still requires further research." (PMID 36902336, 2023). "In summary, we have identified a family with a severe neurodevelopmental disorder due to complete loss of HERC2 and show that this has a significant impact on mitochondrial biogenesis and function, in addition to effects on the levels of known substrate proteins." (PMID 32571899, 2021).
HERC2 also shares sentences with these, for which no sentence is quoted: neurological diseases (4 papers); cutaneous melanoma (3); leukemia (3); bladder cancer (2); glaucoma (2); actinic keratosis (1); acute lymphoblastic leukemia (1); asthma (1); Barrett esophagus (1); chronic obstructive pulmonary disease (1); CNS cancers (1); deafness (1); drug-induced liver injury (1); epilepsy (1); Epileptic encephalopathy (1); genetic disorder (1); hematological cancers (1); infection (1); Kleefstra syndrome (1); language delay (1); liver diseases (1); liver fibrosis (1); lung fibrosis (1); lung squamous cell cancer (1); metastatic colorectal cancer (1); microcephaly (1); Motor delay (1); movement disorder (1); Mowat-Wilson syndrome (1); mucolipidosis type IV (1).
A further 19 diseases each share a sentence with HERC2 in 1 paper.